RGS14 (regulator of G protein signaling 14)
Diseases named in the same sentence as RGS14 in open-access papers:
RGS14 is named in the same sentence as 34 diseases in open-access papers, as found by Europe PMC text mining. Sharing a sentence is not in itself a finding about the gene and the disease. The quoted sentences say what the papers report.
Obesity (3 papers, 2018 to 2025). Accumulation of substantial excess body fat. "In this investigation, we found the RGS14 KO mouse is also protected against obesity and glucose intolerance by promoting a low white adipose tissue (WAT) phenotype with increased brown adipose tissue (BAT)." (PMID 40362353, 2025). "The current study is unique, compared with studies of mice with other RGS isoforms, as the marked protection of RGS14 KO mice against obesity and glucose intolerance was mediated by its BAT." (PMID 40362353, 2025). "The major findings of this investigation demonstrated that the RGS14 KO mouse, a model of healthful longevity, has marked protection against obesity and glucose intolerance, two major factors that enhance healthful longevity." (PMID 40362353, 2025). "RGS14 KO mice exhibit improved exercise capacity, along with protection against obesity and glucose and insulin intolerance, myocardial ischemia, and hypertension." (PMID 39119146, 2024). "The goal of this investigation is to examine whether the RGS14 KO mouse protects against obesity and glucose intolerance, since obesity and diabetes can significantly impact life expectancy and quality of life." (PMID 40362353, 2025). "Thus, two novel mechanisms mediating obesity and glucose intolerance were found, i.e., inhibition of RGS14 and its BAT." (PMID 40362353, 2025). "Thus, disruption of RGS14 is a model of healthful aging, as it not only enhances lifespan, but also protects against obesity and cold exposure and improves metabolism with a key mechanism of increased BAT, which, when removed, eliminates the features of healthful aging." (PMID 29654651, 2018).
Glucose intolerance (2 papers, 2024 to 2025). Glucose intolerance (GI) can be defined as dysglycemia that comprises both prediabetes and diabetes. "The RGS14 KO mice also show protection against glucose intolerance and insulin resistance." (PMID 39119146, 2024).
Hypertension (2 papers, 2024 to 2025). The presence of chronic increased pressure in the systemic arterial system. "The RGS14 KO mouse model is also protected against hypertension, with an important mechanism involving its ability to increase blood flow through angiogenesis." (PMID 39119146, 2024). "The Regulator of G Protein Signaling 14 (RGS14) knockout (KO) mouse is a model of healthful longevity, i.e., its lifespan is prolonged and demonstrates enhanced exercise performance and protection against heart disease and hypertension." (PMID 40362353, 2025).
kidney stone (2 papers, 2019 to 2021). "In summary, this study successfully replicated an association of SNPs in ALPL and RGS14, rs1256328 and rs12654812, with susceptibility to nephrolithiasis in a Taiwanese population." (PMID 31754202, 2019). "It’s very likely that dysfunction of either ALPL or RGS14 influence the homeostasis of calcium and phosphate that increase the risk to nephrolithiasis." (PMID 31754202, 2019). "We observed that the AA genotype of rs12654812 in RGS14 was significantly associated with nephrolithiasis susceptibility in a Taiwanese population, which is also consistent with a previous study on an Icelandic population." (PMID 31754202, 2019). "In addition, subjects carrying the minor AA genotype at rs12654812 (regulator of G protein signaling 14 (RGS14)) have higher susceptibility to nephrolithiasis (OR = 1.91, p = 0.0017)." (PMID 31754202, 2019). "Therefore, further studies are needed to investigate whether rs1256328 (ALPL) and rs12654812 (RGS14) have synergic effects in the susceptibility of nephrolithiasis." (PMID 31754202, 2019). "In addition, the rs12654812 (RGS14) AA genotype was potentially correlated with an increased UCa/UCr compared to the AG or GG genotypes in nephrolithiasis patients (p = 0.0764; adjusted p = 0.0532)." (PMID 31754202, 2019).
neuroblastoma (2 papers, 2017 to 2021). Neuroblastoma (NB) is the most common solid, extracranial childhood tumor. "We previously reported that rat B35 neuroblastoma cells naturally express RGS14 protein at detectable levels." (PMID 28934222, 2017). "Taken together, these findings demonstrate that the polyclonal RGS14 antibody specifically recognizes endogenous RGS14 expressed in rat B35 neuroblastoma cells and validate its use in both western blot and immunofluorescence experiments." (PMID 28934222, 2017). "In summary, we report here for the first time a detailed assessment of the subcellular distribution and dynamic localization of endogenous RGS14 in B35 neuroblastoma cells." (PMID 28934222, 2017). "Here, we report for the first time a comprehensive assessment of the subcellular distribution and dynamic localization of endogenous RGS14 in rat B35 neuroblastoma cells." (PMID 28934222, 2017). "We previously reported that rat B35 neuroblastoma cells naturally express endogenous RGS14 by immunoblot analysis." (PMID 28934222, 2017). "RGS14 is naturally expressed in B35 neuroblastoma cells, where it localizes to chromatin-poor and chromatin-rich regions, nuclear pore complexes, along the nuclear envelope, and in juxtanuclear membranes outside the nucleus, and a subset of RGS14 localizes with active RNA polymerase II." (PMID 34201943, 2021). "Therefore, to define endogenous RGS14 subcellular distribution, we utilized the only neuronal cell line reported to express endogenous RGS14, rat B35 neuroblastoma cells." (PMID 28934222, 2017).
Anxiety (1 paper, 2021). Intense feelings of nervousness, tension, or panic often arise in response to interpersonal stresses. "This suggests that loss of RGS14 augments neophobia (novelty-induced anxiety) and the anxiogenic effect of high-dose cocaine." (PMID 34201943, 2021). "In RGS14-KO mice, both novelty and high-dose cocaine enhanced thigmotaxis (propensity for movement around the periphery of an open field vs. the center), which is an index of anxiety." (PMID 34201943, 2021).
Cognitive impairment (1 paper, 2021). Abnormal cognition is characterized by deficits in thinking, reasoning, or remembering. "There are reports that RGS14 inhibition holds promise for normalizing a cognitive impairment." (PMID 34208998, 2021).
dementia (1 paper, 2024). Loss of intellectual abilities interfering with an individual's social and occupational functions. "Other correlations within the top 10 most significant include PLEKHH3, RGS14, LRCH1, and PCDHB10, notable for their prior implication in dementia and aging." (PMID 38469573, 2024).
dermatitis (1 paper, 2018). An inflammatory process affecting the skin. "It is also important that BAT protects against the aging phenotype, for example, graying and loss of hair, dermatitis, and hunched back, all of which were observed in old WT mice, but not observed in old RGS14 KO mice or in old WT mice, which received BAT transplants." (PMID 29654651, 2018).
dilated cardiomyopathy (1 paper, 2021). Cardiomyopathy which is characterized by dilation and contractile dysfunction of the left and right ventricles. "In humans, RGS14 mRNA is found in the ventricular myocardium of patients with dilated and ischemic cardiomyopathy, while the RGS14 protein is detected in the left ventricle of healthy patients and those with dilated cardiomyopathy." (PMID 34201943, 2021).
glioma (1 paper, 2025). A benign or malignant brain and spinal cord tumor that arises from glial cells (astrocytes, oligodendrocytes, ependymal cells). "In IDH-wt glioma, PGR, COL17A1, and RGS14 showed strong predictive value for recurrence, consistent with their known roles in tumor aggressiveness and therapy resistance." (PMID 41139924, 2025). "In IDH-wt glioma, our approach identified PGR, COL17A1, and RGS14 as key predictive markers for recurrence, consistent with their known roles in tumor aggressiveness and therapy resistance." (PMID 41139924, 2025).
heart failure (1 paper, 2016). Inability of the heart to pump blood at an adequate rate to meet tissue metabolic requirements. "For the first time, our results demonstrated a critical role of RGS14 in the pathophysiology process of cardiac remodelling and heart failure." (PMID 27298141, 2016).
heart hypertrophy (1 paper, 2016). "Our research demonstrated that RGS14 protected the development of cardiac hypertrophy via suppressing the MEK–ERK1/2 signalling pathway in vitro and in vivo." (PMID 27298141, 2016). "Molecular mechanism research revealed that MAPK signalling mediated the effect of RGS14 on cardiac hypertrophy." (PMID 27298141, 2016). "Our major findings demonstrated that the disruption of RGS14 resulted in an exaggerated pathological cardiac remodelling response, whereas the overexpression of RGS14 alleviated the cardiac hypertrophy and dysfunction induced by aortic banding operation." (PMID 27298141, 2016). "The protective effect of RGS14 on pressure overload-induced cardiac hypertrophy in the RGS14-TG1 mice was significantly weaker than in the RGS14-TG2 mice, suggesting a possible gene doses effect." (PMID 27298141, 2016). "We also examined the hypertrophic response of RGS14-TG1 mice (RGS14 expression is 2.5-fold higher than that of CRMC) to evaluate the relevance of RGS14 expression in cardiac hypertrophy." (PMID 27298141, 2016). "Moreover, the extent of aortic banding-induced cardiac hypertrophy and fibrosis was exacerbated in RGS14 knockout mice, whereas RGS14 transgenic mice exhibited a significantly alleviated response to pressure overload." (PMID 27298141, 2016). "Furthermore, RGS14 knockout aggravated cardiac hypertrophy after aortic banding, and RGS14 cardiomyocyte-specific overexpression significantly alleviated cardiac remodelling in vivo, which revealed a protective role of RGS14 in cardiac remodelling." (PMID 27298141, 2016). "We are unable to exclude the possibility that RGS14 in fibroblasts might contribute to cardiac hypertrophy via other pathways." (PMID 27298141, 2016). "We first observed that the protein level of RGS14 was decreased in the hearts of DCM patients, which suggested that RGS14 might be involved in the process of cardiac hypertrophy." (PMID 27298141, 2016). "A limitation of this study is that the up-stream regulatory mechanism for RGS14-mediated protection of heart hypertrophy was not elucidated, because we only focused on the effect of RGS14 on the development of heart remodelling in this study." (PMID 27298141, 2016).
hepatocellular carcinoma (1 paper, 2025). A malignant tumor that arises from hepatocytes. "To investigate the regulatory role of RGS14 in hepatocellular carcinoma progression through the cAMP/PKA/CREB axis, we used an AC inhibitor and agonist for experimental verification." (PMID 40312502, 2025). "However, the role of RGS14 in hepatocellular carcinoma (HCC) progression and its underlying mechanisms remain unclear." (PMID 40312502, 2025).
liver fibrosis (1 paper, 2022). "The CISTR, IFT140, and RGS14 genes are potential novel candidate BDM biomarkers for liver fibrosis and these pilot data suggest further work on BDM biomarkers is warranted." (PMID 35433752, 2022). "The CISTR, IFT140, and RGS14 genes are likely novel candidate blood methylation biomarkers for the diagnosis of liver fibrosis in NAFLD." (PMID 35433752, 2022). "The roles of the CISTR, IFT140, and RGS14 genes in the onset of liver fibrosis in NAFLD patients and their roles in the blood and the relationship with liver fibrosis remain unclear." (PMID 35433752, 2022). "Genes such as CISTR, IFT140, and RGS14 that contain DMPs in the blood DNA of NAFLD patients may provide clues to investigate the role of DNA methylation in the progression of liver fibrosis." (PMID 35433752, 2022). "Therefore, the CISTR, IFT140, and RGS14 genes may be potential novel candidate blood methylation biomarkers for the diagnosis of liver fibrosis in NAFLD." (PMID 35433752, 2022).
sarcoidosis (1 paper, 2024). Sarcoidosis is a multisystemic disorder of unknown cause characterized by the formation of immune granulomas in involved organs. "Novel immune related genes and miRNAs including LYST, RGS14, SLFN12L, and hsa-miR-199b-5p, distinguished sarcoidosis from controls." (PMID 39080656, 2024). "Our integrated model revealed several novel genes and miRNAs between sarcoidosis and controls, including LYST, RGS14, SLFN12L, and hsa-miR-199b-5p." (PMID 39080656, 2024).
status epilepticus (1 paper, 2023). Status epilepticus is defined as a continuous seizure lasting more than 30 min, or two or more seizures without full recovery of consciousness between any of them. "Using kainic acid (KA) to induce status epilepticus (KA-SE) in mice, we show loss of RGS14 (RGS14 KO) accelerated onset of limbic motor seizures and mortality compared to wild type (WT) mice, and that KA-SE upregulated RGS14 protein expression in CA2 and CA1 PCs of WT." (PMID 36778349, 2023).
ulcer (1 paper, 2022). "The safety of the recombinant viruses was tested in 1-month-old lambs and results demonstrated that no ORFV associated symptoms such as ulcer and proliferative scabby lesions were induced by either rGS14-ΔCBP, rGS14-ΔGIF or rGS14-ΔCBP-ΔGIF at 21 days post-infection." (PMID 36119021, 2022).
tumor (5 papers, 2021 to 2025). "Analysis of publicly accessible databases revealed markedly elevated RGS14 mRNA levels in tumor samples compared with those in control samples across both the TCGA and GTEx datasets." (PMID 40312502, 2025). "Western blotting analysis revealed that RGS14 expression gradually increased in tumor-adjacent tissues, HCC tissues, and PVTT tissues." (PMID 40312502, 2025). "Similar to RGS14 mRNA expression, RGS14 protein expression was significantly higher in 16 pairs of HCC tissues than in tumor-adjacent tissues, as shown by immunoblotting." (PMID 40312502, 2025). "Compared with those in the control group, the tumor weight and volume in the RGS14-knockdown group were markedly lower." (PMID 40312502, 2025). "To investigate the major pathway by which RGS14 influences tumor behavior, we performed transcriptome sequencing of RGS14-knockdown (shRGS14) and shNC-transfected MHCC97H cells." (PMID 40312502, 2025). "To further investigate the role of RGS14 in tumor progression, we utilized an in vivo xenograft model." (PMID 40312502, 2025). "Univariate analysis revealed that the AFP level, tumor size, tumor number, TNM stage, vascular invasion, satellite lesions, and RGS14 expression were significantly associated with OS in HCC patients." (PMID 40312502, 2025). "The results demonstrated that RGS14 knockdown significantly inhibited tumor growth." (PMID 40312502, 2025). "In addition, multivariate analysis revealed that only the RGS14 level, tumor number, and tumor size were independent predictors of OS in HCC patients." (PMID 40312502, 2025). "However, the role of RGS14 in the tumor tissues is yet to be elucidated." (PMID 35370869, 2022). "BALB/c nude mice were subcutaneously injected with either RGS14-knockdown or control MHCC97H cells, and tumor growth was monitored over time." (PMID 40312502, 2025). "Among the top 10 upregulated proteins, RGS14, a critical modulator of GPCR-Gα signaling cascades, has pivotal functions in promoting tumor progression." (PMID 40312502, 2025).
cancer (2 papers, 2019 to 2021). A tumor composed of atypical neoplastic, often pleomorphic cells that invade other tissues. "However, little work has been done to elucidate the role of RGS14 in cancer." (PMID 31130992, 2019).
cardiovascular disease (2 papers, 2016 to 2024). "However, the role of RGS14 in cardiovascular diseases remains unclear." (PMID 27298141, 2016).
infection (2 papers, 2022 to 2025). The state of being infected such as from the introduction of a foreign agent such as serum, vaccine, antigenic substance or organism. "The group of animals inoculated with rGS14-ΔCBP-ΔGIF all remained clinically healthy, not exhibiting any significant signs of disease during the 14-day observational period except anorexia and a slight fever by day 5 post-infection." (PMID 36119021, 2022).
metabolic disorders (1 paper, 2025). "This work opens the door to future development of RGS14 inhibitors as potential therapeutics for central nervous system and metabolic disorders." (PMID 40848973, 2025).
RGS14 also shares sentences with these, for which no sentence is quoted: Alzheimer disease (1 paper); Calcium nephrolithiasis (1); diabetes (1); glioblastoma multiforme (1); glomerulosclerosis (1); heart disease (1); inflammatory bowel disease (1); ischemia (1); ischemic cardiomyopathy (1); male infertility (1); orf (1).